UBASH3B (ubiquitin associated and SH3 domain containing B)
Description:
Interferes with CBL-mediated down-regulation and degradation of receptor-type tyrosine kinases. Promotes accumulation of activated target receptors, such as T-cell receptors and EGFR, on the cell surface. Exhibits tyrosine phosphatase activity toward several substrates including EGFR, FAK, SYK, and ZAP70. Down-regulates proteins that are dually modified by both protein tyrosine phosphorylation and ubiquitination.
Synonyms: STS-1; TULA-2; KIAA1959; STS1; TULA2; p70
Tractability: Small molecule: a structure with a bound ligand is known. PROTAC: ubiquitination databases record sites on it; its protein half-life has been measured.
Target class: Enzyme; Hydrolase
Gene: Protein-coding gene on chromosome 11 (122,655,722 to 122,814,473, forward strand). Ensembl gene ENSG00000154127.
Subcellular location: Cytoplasm; Nucleus
Subcellular location (Human Protein Atlas): Cytosol; Nuclear bodies; Nucleoplasm
Gene Ontology:
Molecular function: identical protein binding; protein binding; protein tyrosine phosphatase activity; phosphoprotein binding; ubiquitin protein ligase binding
Biological process: collagen-activated tyrosine kinase receptor signaling pathway; negative regulation of bone resorption; negative regulation of signal transduction; platelet aggregation; regulation of osteoclast differentiation; regulation of release of sequestered calcium ion into cytosol
Cellular component: cytoplasm; nucleus
Genetic constraint (gnomAD): Loss-of-function variants: 36 observed, 81.93 expected, observed/expected ratio (o/e) 0.44, 90% interval 0.34 to 0.58. The upper end of that interval is the gene's LOEUF score, 0.58, which puts it in group 2 of 6, group 1 being the genes least tolerant of losing a copy. Missense variants: 648 observed, 824.22 expected, observed/expected ratio (o/e) 0.79, 90% interval 0.74 to 0.84. Synonymous variants: 300 observed, 318.97 expected, observed/expected ratio (o/e) 0.94, 90% interval 0.86 to 1.03.
Homologues: Orthologues: chimpanzee UBASH3B (99% identical), macaque UBASH3B (99% identical), rabbit UBASH3B (98% identical), dog UBASH3B (97% identical), pig UBASH3B (96% identical), mouse Ubash3b (96% identical), guinea pig UBASH3B (92% identical), rat Ubash3b (90% identical), tropical clawed frog ubash3b (82% identical), zebrafish ubash3ba (73% identical), zebrafish ubash3bb (72% identical), Drosophila melanogaster Epp (39% identical), and 1 more. Paralogues in human: UBASH3A (45% identical).
Diseases named in the same sentence as UBASH3B in open-access papers:
UBASH3B is named in the same sentence as 38 diseases in open-access papers, as found by Europe PMC text mining. Sharing a sentence is not in itself a finding about the gene and the disease. The quoted sentences say what the papers report.
prostate carcinoma (6 papers, 2019 to 2025). A carcinoma that arises from epithelial cells of the prostate gland. "For example, in a ceRNA network focused on the prostate cancer biomarker UBASH3B (Ubiquitin-associated and SH3 domain-containing B), UBASH3B directly engages with the immune-related gene LCP2, playing a role in mediating inflammatory responses." (PMID 40428349, 2025). "It is well known that UBASH3A is primarily expressed in T-cells and is associated with autoimmune diseases, whereas UBASH3B is ubiquitously expressed and involved in regulating T-cell receptor signalling and prostate cancer." (PMID 38339213, 2024). "Likewise, in prostate cancer, high UBASH3B expression is associated with poor clinical outcomes, including reduced overall survival." (PMID 40885971, 2025). "Additionally, UBASH3B has been identified as a potential prognostic biomarker in prostate cancer and is associated with tumor-infiltrating immune cells." (PMID 38339213, 2024). "Additionally, bioinformatics analyses have revealed that miR-192-5p is associated with ubiquitin-associated and SH3 domain-containing B (UBASH3B), a poor prognostic marker of prostate cancer." (PMID 33708127, 2021). "Our results suggested that UBASH3B may be a novel prognostic marker and was associated with tumor-infiltrating immune cells in prostate cancer." (PMID 32010618, 2019). "It was suggested that UBASH3B could drive prostate cancer metastasis, so the mechanism of tumor metastasis that is associated with UBASH3B may be our next investigation." (PMID 32010618, 2019). "Elevated UBASH3B expression has been documented in various cancers, fostering invasive and metastatic behavior and correlating with poor survival in breast and prostate cancer patients." (PMID 39343960, 2024). "UBASH3B has been found to be a novel prognostic biomarker correlated with immune infiltrates in prostate cancer." (PMID 38339213, 2024). "In this study, we identified UBASH3B as a novel potential prognostic biomarker for prostate cancer and investigated the correlation between UBASH3B and tumor-infiltrating immune cells in PCa." (PMID 32010618, 2019). "Relationship between UBASH3B expression level and clinicopathological variables and in prostate cancer patients." (PMID 32010618, 2019). "Kaplan-Meier analysis suggested that prostate cancer patients with high UBASH3B expression level experienced a significantly shorter overall survival of 5-year than those with low UBASH3B levels (p = 0.042)." (PMID 32010618, 2019). "We performed immunohistochemistry staining for UBASH3B expression in prostate cancer and BPH tissues." (PMID 32010618, 2019). "Kaplan-Meier survival analysis indicated that UBASH3B is a prognostic factor for 5-year survival in patients with prostate cancer." (PMID 32010618, 2019). "Based on the expression level of UBASH3B, we found six types of tumor-infiltrating immune cells in prostate cancer tissues, including B cells, CD4+ T cells, CD8+ T cells, macrophages, neutrophil, and dendritic cells." (PMID 32010618, 2019). "Quantitative analysis of IHC found that the expression of UBASH3B was significantly upregulated in the prostate cancer tissues compared with BPH." (PMID 32010618, 2019). "How UBASH3B participate in tumor microenvironment and influence tumor-infiltrating immune cells in prostate cancer should be explored." (PMID 32010618, 2019). "UBASH3B has been detected in prostate cancer cell lines and UBASH3B knockdown can decrease EGF-induced invasion and form tumor spheres in PC3 and DU145 cells." (PMID 32010618, 2019). "Real time PCR and western blot analysis results of our study showed mRNA and protein expression of UBASH3B were increased in prostate cancer samples as compared with that in benign prostatic hyperplasia samples." (PMID 32010618, 2019). "This suggests that UBASH3B may be a potential biomarker for prostate cancer and is involved in the immune response in cancer." (PMID 32010618, 2019).
prostate carcinoma (continued). "In conclusion, our study has indicated that UBASH3B may represent a potential biomarker that contributes to poor prognosis for prostate cancer." (PMID 32010618, 2019). "In this study, we investigated mRNA and protein expression of UBASH3B in prostate cancer." (PMID 32010618, 2019). "UBASH3B may also play a vital role in the microenvironment of prostate cancer through regulating tumor-infiltrating of immune cells, suggesting UBASH3B as a therapeutic target to modulate anti-tumor immune response." (PMID 32010618, 2019). "However, the function of UBASH3B in prostate cancer (PCa) and the correlation between UBASH3B and tumor-infiltrating immune cells still remain unclear." (PMID 32010618, 2019). "TIMER was used for correlation analysis and it indicated that UBASH3B was significantly correlated with LCP2 (p = 3.37e-40, cor = 0.547), PIK3CG (p = 2.44e-38, cor = 0.536), and BIRC3 (p = 0, cor = 0.534) in prostate cancer." (PMID 32010618, 2019).
leukemia (5 papers, 2019 to 2025). A malignant (clonal) hematologic disorder, involving hematopoietic stem cells and characterized by the presence of primitive or atypical myeloid or lymphoid cells in the bone marrow and the blood. "Herein, we showed that loss of FLI1 and consequently its downstream target UBASH3B in leukemia cells increased AP1 expression, leading to proliferation suppression and increased apoptosis." (PMID 38461240, 2024). "Functional studies linked UBASH3B expression to evaluate diseases states such as in thrombosis, leukemia, and triple-negative breast cancer." (PMID 32010618, 2019). "UBASH3B’s involvement in the pathogenesis of various tumors, including breast cancer and leukemia, has been documented." (PMID 39343960, 2024). "Previously, we showed that UBASH3B upregulation increases PKCẟ degradation, which increased drug resistance and leukemia cell survival." (PMID 38461240, 2024). "In this study, we show that leukemias expressing high FLI1 produce either higher UBASH3B or lower UBASH3A." (PMID 38461240, 2024). "Interaction between UBASH3B and PKCẟ accelerated ubiquitination of this kinase, resulting in leukemia cell survival and drug resistance." (PMID 38461240, 2024). "UBASH3B also activates the oncogene SYK to promote leukemia growth." (PMID 38461240, 2024). "UBASH3B also regulates myeloid proliferation through UBASH3B-CBL axis in human pre-leukemia." (PMID 32010618, 2019). "As FLI1 knockdown blocks leukemia cell proliferation, we next examined impact of UBASH3A and UBASH3B on cell growth." (PMID 38461240, 2024). "The balance between oncogenic and tumor suppressor activity of UBASH3B and UBASH3A, respectively, likely contributes to FLI1-induced leukemia cell proliferation." (PMID 38461240, 2024). "In contrast to solid tumors, the data presented herein suggest an inhibitory role for HSPA1B in leukemia progression, whose expression depend upon the level of UBASH3A and UBASH3B." (PMID 38461240, 2024). "UBASH3B also positively regulates the SYK gene expression and its inhibition suppresses leukemia progression." (PMID 38461240, 2024). "UBASH3B functions either as a tumor suppressor in some cancers, such as TCR and LUAD, by inhibiting oncogenic kinase pathways, and enhancing mitochondrial metabolism, while paradoxically functioning as an oncogene in other cancers such as leukemia, prostate, breast, and head and neck cancers." (PMID 40885971, 2025).
triple-negative breast carcinoma (4 papers, 2019 to 2025). An invasive breast carcinoma which is negative for expression of estrogen receptor (ER), progesterone receptor (PR), and human epidermal growth factor receptor 2 (HER2). "Notably, UBASH3B, known for its tyrosine protein phosphatase activity, has been implicated as an oncogenic driver in triple-negative breast cancer invasion and metastasis." (PMID 39343960, 2024). "Specifically, overexpression of UBASH3B has been shown to promote invasion and metastasis in triple-negative breast cancer and enhance proliferation in acute myeloid leukemia." (PMID 40885971, 2025). "UBASH3B is a functional target for drug-resistance and downregulated anti-invasive microRNA200a in triple-negative breast cancer." (PMID 32010618, 2019). "UBASH3B has also emerged as a key oncogenic player in breast cancer progression, exhibiting distinct roles in both estrogen-receptor (ER)-positive breast cancer and triple-negative breast cancer (TNBC)." (PMID 40885971, 2025). "miR-200a targets UBASH3B against invasion and is downregulated in triple-negative breast cancer." (PMID 32010618, 2019). "Similarly, in triple negative breast cancer, higher expression of UBASH3B promotes dephosphorylation and inactivation of CBL, which in turn loses ability to ubiquitinate and induce degradation of the epidermal growth factor receptor (EGFR), leading to accelerated cancer progression." (PMID 38461240, 2024).
acute myeloid leukemia (3 papers, 2019 to 2025). Acute myeloid leukemia (AML) is a group of neoplasms arising from precursor cells committed to the myeloid cell-line differentiation. "In acute myeloid leukemia (AML), UBASH3B contributes to myeloid proliferation and leukemogenesis through CBL inactivation and AML1-ETO-induced signaling." (PMID 40885971, 2025). "In acute myeloid leukemia (AML), UBASH3B is upregulated by AML1-ETO fusion protein to promote the growth of AML cells by functionally regulating CBL." (PMID 32010618, 2019). "In Acute Myeloid Leukemia (AML) and whole blood cells, the expression of FLI1 was significantly correlated with the level of UBASH3B." (PMID 38461240, 2024). "In Acute Myeloid Leukemia (AML) induced by the oncogene AML-ETO, UBASH3B inactivates CBL, which is predicted to inhibit the ubiquitination of its downstream effectors responsible for leukemogenesis." (PMID 38461240, 2024).
breast carcinoma (3 papers, 2016 to 2024). "Datasets from The Cancer Genome Atlas (TCGA) and Gene Expression Omnibus (GEO) were re-analyzed to explore the association between UBASH3B and the progression of ER+ breast cancer." (PMID 29492198, 2018). "In the present study, we demonstrate that high expression of UBASH3B is associated with poor prognosis of ER+ breast cancer and tamoxifen resistance." (PMID 29492198, 2018). "The goal of the present study was to clarify the prognostic value of UBASH3B in ER+ breast cancer and elucidate its association with tamoxifen efficacy." (PMID 29492198, 2018). "Close family members of CLIP4/UBASH3B were also found to be associated with metastasis in breast cancer, and the same study also suggested that CLIP4 expression could stimulate tumor metastasis in some tumor types." (PMID 27283491, 2016). "By performing GSEA using gene expression data from 623 breast cancer samples, we show high expression of UBASH3B is negatively correlated with genes down regulated in tamoxifen resistant patients, which indicates the association between UBASH3B and tamoxifen resistance." (PMID 29492198, 2018). "Taken together, these findings suggest a potential role of UBASH3B in the progression of ER+ breast cancer." (PMID 29492198, 2018). "Cisplatin is a potential therapeutic option for the management of breast cancer patients with high expression of UBASH3B." (PMID 29492198, 2018). "This diagram shows that UBASH3B is down-regulated by ER and cisplatin and can promote breast cancer progression through EGFR." (PMID 29492198, 2018). "Findings in previous sections show potential roles of UBASH3B plays in the progression and tamoxifen resistance in ER+ breast cancer." (PMID 29492198, 2018). "UBASH3B is negatively regulated by ER and confers poor outcome in ER+ breast cancer patients." (PMID 29492198, 2018). "In an effort to find available chemotherapeutics that could be used in adjuvant setting for the management of breast cancer patients with high expression of UBASH3B, data mining from The Comparative Toxicogenomics Database (CTD) was performed." (PMID 29492198, 2018). "Since high expression of UBASH3B confers poor prognosis in ER+ breast cancer and tamoxifen is a first-line drug for the management of ER+ patients, UBASH3B expression may be associated with tamoxifen efficacy." (PMID 29492198, 2018). "Subset analysis found that UBASH3B also has prognostic value on both lymph node positive and negative sub-populations with ER+ breast cancer." (PMID 29492198, 2018). "Subset analysis indicated that UBASH3B expression was also correlated with DMFS of both lymph node – (left, P = 0.015) and lymph node + (right, P = 0.046) patients with ER+ breast cancer in Van dataset." (PMID 29492198, 2018).
Thrombocytopenia (2 papers, 2021 to 2022). A reduction in the number of circulating thrombocytes. "Previous studies have demonstrated that heparin‐induced thrombocytopenia and adverse drug reaction pathways were associated with UBASH3B gene." (PMID 36453946, 2022).
acute lymphoblastic leukemia (1 paper, 2021). Leukemia with an acute onset, characterized by the presence of lymphoblasts in the bone marrow and the peripheral blood. "The human UBASH3B gene encodes for STS-1 phosphatase (suppressor of T-cell receptor signaling 1), the high expression of which has been correlated with the p190BCR-ABL1 form in acute lymphoblastic leukemia (ALL) patients’ samples, but is usually considered a BCR-ABL1 interactor." (PMID 34065882, 2021).
autoimmune disease (1 paper, 2024). A disorder resulting from loss of function or tissue destruction of an organ or multiple organs, arising from humoral or cellular immune responses of the individual to their own tissue constituents. "While UBASH3B’s role in autoimmunity appears to be limited, UBASH3A has been associated with several autoimmune diseases, particularly in the regulation of T-cell function in the context of type 1 diabetes, systemic lupus erythematosus, celiac disease, rheumatoid arthritis, and vitiligo." (PMID 38339213, 2024).
Behçet's disease (1 paper, 2009). "The SNPs rs9513584 and rs4936742 located within the genes UBAC2 (ubiquitin-associated domain [UBA] containing 2) and UBASH3B (ubiquitin associated and SH3 domain containing, B) were also associated with Behçet's disease with P values of 5.8 × 10-3 and 1.5 × 10-3, respectively." (PMID 19442274, 2009). "However, the data suggest that the risk allele in rs4936742 is more common in patients with eye involvement and with vascular involvement, suggesting that the disease-associated polymorphism in UBASH3B might predispose to eye and vascular complications in patients with Behçet's disease." (PMID 19442274, 2009).
cholangiocarcinoma (1 paper, 2020). A carcinoma that arises from the intrahepatic biliary tree (intrahepatic cholangiocarcinoma) or from the junction, or adjacent to the junction, of the right and left hepatic ducts (hilar cholangiocarcinoma). "However, CD36, GGCX, UBASH3B, DBN1, PTTG1, CCNA2, and SPATS2 are found in other tumors to regulate tumor progression, which may also regulate cholangiocarcinoma progression and affect the recurrence of CCA." (PMID 32071556, 2020).
erythroleukemia (1 paper, 2024). Acute erythroid leukemia characterised by the presence of at least 50% erythroid precursors and at least 20% myeloblasts in the bone marrow. "FLI1 promotes erythroleukemia progression in part by modulating expression of the oncogenic UBASH3B and tumor suppressor UBASH3A." (PMID 38461240, 2024). "We have previously shown that Protein Kinase C Delta (PKCẟ) downregulation in TPA (4b-12-O-tetradecanoylphobol-13-acetate)-resistant cell lines, can inhibit erythroleukemia when paired with UBASH3B knockdown." (PMID 38461240, 2024). "UBASH3B was found to be a direct target of FLI1, and its activation promotes erythroleukemia growth." (PMID 38461240, 2024). "UBASH3B and UBASH3A are found to act as an oncogene and tumor suppressor, respectively, and their combined effect determines erythroleukemia progression downstream of FLI1." (PMID 38461240, 2024). "FLI1 is shown in this study to promote erythroleukemia progression by inhibiting UBASH3A and expression and inducing UBASH3B expression." (PMID 38461240, 2024).
glioma (1 paper, 2024). A benign or malignant brain and spinal cord tumor that arises from glial cells (astrocytes, oligodendrocytes, ependymal cells). "Higher UBASH3B in AML, Pancreatic Adenocarcinoma, Brain lower grade glioma, Pancreatic adenocarcinoma and Lung squamous cell carcinoma were also correlated with worse prognosis." (PMID 38461240, 2024).
hepatocellular carcinoma (1 paper, 2025). A malignant tumor that arises from hepatocytes. "Similarly, another study in hepatocellular carcinoma identified UBASH3B as a central component of the immunosuppressive signaling axis involving NRI1I2, CEACAM1, and HAVCR2." (PMID 40885971, 2025).